SOX2 (SRY-box transcription factor 2)
Diseases named in the same sentence as SOX2 in open-access papers (continued):
Sharing a sentence is not in itself a finding about the gene and the disease.
glioma (continued). "Nearly all SOX genes, including SOX1, SOX2, SOX7, and SOX10, have been shown to influence glioma progression and exhibit oncogenic functions across multiple cancer types." (PMID 40159622, 2025). "The expression of various glioma stemness markers – NANOG (4-fold increase), SOX2 (3-fold increase), SOX2-OT (15-fold increase) and CD133 (3-fold increase) – were also significantly increased in high-grade glioma samples compared to the controls." (PMID 41034696, 2025). "Our findings of ATRA-induced downregulation of SOX2 and Nestin mRNA are broadly consistent with previous reports indicating ATRA can induce differentiation in various glioma cell line models." (PMID 40422249, 2025). "Genes linked to stemness and therapy resistance included CD133 (PROM1), SOX2, Nestin, OLIG2, and Musashi-1, all of which support the persistence of glioma stem-like cell populations and drive recurrence." (PMID 41179304, 2025). "Overall, NOTCH1 and SOX2, key regulators of EMT, are most frequently altered in both HGG and LGG, indicating their universal role across different glioma tumors." (PMID 40679044, 2025). "To generate and characterize a HGG model, we used the glioma stem cell line model GSC23, previously shown to exhibit high levels of Sox2 and a strong tropism for white matter tracts." (PMID 41375052, 2025). "HIF-1α appears to bind to the promoter of CD133 (a marker gene of CSCs), promoting the production of CD133 +glioma stem-like cells through OCT4 and SOX2." (PMID 38716541, 2024). "In CD133-positive glioma stem cells (GSCs), the miR-145/OCT4/SOX2 axis confers radio-chemo resistance, while inhibition of this axis increases the sensitivity to temozolomide (TMZ) and radiation, following a decreased expression of ABCG2, MDR1 and Bcl2." (PMID 38331879, 2024). "Suppressing NEAT1 impedes the migration and invasion capabilities of glioma cells by modulating the expression of SOX2, targeted by miR-132, underscoring NEAT1’s significance in glioma progression and its potential as a therapeutic target." (PMID 39015773, 2024). "Further IHC analysis of human glioma specimens indicated a positive correlation between TGFBI and SOX2 expression level, as well as CD133." (PMID 39346536, 2024). "They further showed that in Sox2-negative glioma cell lines, treatment with the DNA methyl-transferase inhibitor, 5-azacitidine (5-AZA), resulted in increased Sox2 expression at the mRNA and protein levels, whereas treatment with TSA had no such effect." (PMID 38473392, 2024). "TAGLN co‐distributed with GSC markers CD133, CD15, SOX2, and OLIG2 in glioma cells, suggesting that TAGLN was preferentially expressed in GSCs in patient tissues." (PMID 38087889, 2024). "Gliomasphere line specific (EGFR) and cell cycle markers (MKI67, TOP2A) dominated clustering and we noted enrichment of glioma stem cell (PTPRZ1, SOX2) and astrocytic markers (GFAP, S100B) in GS025." (PMID 38856710, 2024). "EGFR, BCAN, SOX2, PTN and CCN3 were found to be highly elevated in the glioma tumorous tissue with prominent fold change value, while other DE-ARGs, such as CLU, SCG3, showed no distinct expression alteration." (PMID 39033204, 2024). "In order to determine the presence of glioma stem cells, we also stained for SRY (sex determining region Y)-box 2 (SOX2)." (PMID 39196480, 2024). "Positive correlation between OCT4 and SOX2 expression in GBM patients suggests an important role of OCT4 and SOX2 in the pathology of glioma." (PMID 39588508, 2024). "Stemness-related genes, such as SOX2 and POUF2, are essential for glioma propagation, and MYC regulates the expression of these genes in glioma cells." (PMID 39501082, 2024). "In particular, the CSC markers CD133 and Sox2 were upregulated in U87MG and U251 glioma cells stably overexpressing HSP90 (oe-HSP90) and downregulated after HSP90 knockdown (sh-HSP90)." (PMID 38102125, 2023).
glioma (continued). "METTL3 silencing reduced the expression of the glioma reprogramming factors POU3F2, SOX2, SALL2 and OLIG2, and suppressed GSC proliferation in neurosphere assays derived from human glioma cell lines." (PMID 37444417, 2023). "CRISPR-Cas9 technology was utilized to generate SOX2-KO cells from glioma cell lines (U251, LN229, and CCF) and primary GSCs, which exhibit relatively higher SOX2 expression and possess higher HCMV infection efficiency than the other three cell lines." (PMID 37058447, 2023). "As expected, GSCAR expression positively correlated with glioma stem cell biomarkers, including CD133, CD44, NANOG, ALDH1, Oct4, SOX2, and c-Myc." (PMID 37063420, 2023). "Together, these data demonstrate that SOX2 positively increases both HCMV gene expression and replication in glioma cells." (PMID 37058447, 2023). "As expected, the SOX2 mRNA levels were much higher in HGG samples than in low-grade glioma (LGG) and non-glioma (NG) samples." (PMID 37058447, 2023). "Functional analyses also revealed a strong inverse correlation between the expression of PR-LncRNAs and SOX family members (SOX1, SOX2, and SOX9) in glioma clinical biopsies and glioma cells." (PMID 37047365, 2023). "Studies have shown dense infiltration of Tregs in glioma, where they induce the expression of the stemness‐related genes CD133, nestin, SOX2, and so on by the NF‐κB‐IL6‐STAT3 signaling pathway, thereby increasing cancer stemness and promoting tumor growth." (PMID 37576862, 2023). "Tumors from a cohort of 144 glioma subjects were categorized according to the IE1 and SOX2 levels and assigned to four groups: IE1low/SOX2low, IE1low/SOX2high, IE1high/SOX2low, IE1high/SOX2high." (PMID 37058447, 2023). "Our findings suggested that SOX2 promotes HCMV gene expression and replication in gliomas by downregulating PML." (PMID 37058447, 2023). "Due to the SOX2-mediated downregulation of PML and Sp100, the PML-NBs formation is greatly reduced in glioma cells, removing the restriction on HCMV gene expression." (PMID 37058447, 2023). "Treatment of glioma cells with OPC-derived conditioned medium significantly increased the expression of typical stemness genes (e.g., Nanog, Sox2, Oct3/4, and Bmi1), sphere-forming ability, and cell viability of glioma cells and promoted chemo-radioresistance." (PMID 38020906, 2023). "Though cell experiments, we found that the depletion of A3C leads to the downregulation of markers of glioma stem cells (CD133 and SOX2) and a decrease in stemness, underscoring its potential importance in maintaining glial stemness." (PMID 37809064, 2023). "In GBM, the proteins Sox2, CD133, SSEA1, CD49f, Musashi-1, and Nestin are considered to be glioma stem cell CSC markers." (PMID 36900417, 2023). "Moreover, SOX2 may enhance the migratory and invasive capacity of glioma cells." (PMID 34953010, 2022). "This delivered miR-145 and miR-124 notably decreased the migration of glioma cells by targeting Synaptonemal Complex Protein 1 (SCP-1) and SRY-Box Transcription Factor 2 (Sox2) genes." (PMID 36536420, 2022). "We show that the miR-10b-5p onco-miR is induced by SOX2, directly targets TET2, mediates onco-methylation, GSC induction and glioma malignancy." (PMID 35136034, 2022). "METTL3 is also upregulated in glioblastoma, and silence of METTL3 inhibits the growth of glioma stem cells by downregulating POU3F2, SOX2, SALL2, OLIG2, and other glioma recombinant factors." (PMID 35571490, 2022). "In another study of gliomas, treatment with an inhibitor of the Hh pathway decreased expression of OCT4, SOX2, and NANOG in GICs 49, further supporting that this pathway regulates stemness." (PMID 36118530, 2022). "The data showed that IPS reprogramming factors and pluripotency-related genes (POU5F1, SOX2, KLF4, MYC and NOTCH1) were detected in almost all histologic types and grades of gliomas." (PMID 36435765, 2022).
glioma (continued). "HDAC6 was also enriched in glioma stem cells,and its expression positively correlated with several GSC markers(SOX2, SOX9, CD133, NESTIN, and OCT4)." (PMID 35786935, 2022). "The redundancy between members of the SOXB1 subgroup enhances their interactions with other genes involved in the renewal and proliferation of glioma stem cells (SOX1, SOX2, and SOX3)/Cdks/cyclins." (PMID 35392088, 2022). "We also discovered the molecular mechanism in which SOX2 binds to the CD39 promoter to regulate eATP level, and evaluated the enhanced immune response by inhibiting CD39 after ADM treatment in a mouse glioma model." (PMID 35159053, 2022). "It was found that lncRNA SOX2OT reduced the methylation level of SOX2 by interacting with ALKBH5, thus improving the SOX2 expression and activating the Wnt5a/β-catenin signaling pathway to promote TMZ resistance in glioma cells." (PMID 35912271, 2022). "The m6A writer METTL3 is elevated in glioma stem-like cells (GSCs), where it mediates GSC maintenance and dedifferentiation by regulating SOX2 mRNA stability." (PMID 35717510, 2022). "It has also been reported that long non‐coding RNA PVT1 induces up‐regulation of SOX2 expression through the miR‐365/ELF4 axis, thereby promoting the maintenance of stemness and TMZ resistance in glioma cells." (PMID 36184801, 2022). "In glioma cell cultures, silencing of uPAR and cathepsin B downregulates the expression of CD133, Nestin, Sox2 and Bmi1 and reduces the number of glioma-initiating cells." (PMID 35493073, 2022). "DUXAP10 knockdown remarkably reduced the activity of ALDH and the expression of stemness markers (Sox2, CD133, Oct4) in glioma cells." (PMID 35186937, 2022). "We had found from in vitro studies that RIP2 enhances the expression of glioma stem cell marker proteins CD133 and SOX‐2 through the NF‐κB pathway." (PMID 36184801, 2022). "BMP‐4 reduced the expression of glioma stem cell marker mRNAs, including PROM1, OLIG2, and SOX2, in TGS‐01 as well as in TGS‐04 cells." (PMID 34214250, 2022). "Propofol treatment upregulated the levels of the glioma marker, GFAP, and glioma stem cell markers, Oct4 and Sox2, expressed in PDX tumors." (PMID 35927718, 2022). "Consistent with the previous findings (above), the mRNA levels of SOX2 and SOX3 were higher in glioma cell lines compared to other cancer types." (PMID 34953010, 2022). "Inhibiting miR-10b-5p partially rescues the reduction in 5hmC expression observed in GSCs expressing transgenic SOX2, thus implicating miR-10b-5p as a critical mediator of SOX2-induced onco-methylation, GSC induction and glioma malignancy." (PMID 35136034, 2022). "Infiltrating Treg cells in glioma upregulate the expression of the core stem cell markers CD133, SOX2 and NESTIN in glioma stem cells, which are enriched by TGF-β secretion." (PMID 34202411, 2021). "The level of expression glioma-characteristic genes (e.g. CD34, GFAP, OLIG2, MAP2, MKI67, RBFOX3, SOX2, SYN; Suppl." (PMID 34545083, 2021). "Some transcriptional factors with well-recognized functions in embryonic development, such as Nanog, Oct4, Sox2, STAT3, have been identified as oncogenic drivers which can affect the fate of glioma stem cells and regulation of glioma development." (PMID 34408983, 2021). "In glioma cells A172 as well as U87MG, transfections of SNHG6 siRNA markedly reduced the levels of Sox2." (PMID 34485294, 2021). "The markers were glioma stem cell markers (CD133 and Msh1), neuronal lineage markers (nestin, sox1, sox2, and pax6), and differentiated markers (GFAP, Tuj1, and Olig123)." (PMID 33575478, 2021).
glioma (continued). "METTL3 enhances the m6A methylation by improving the stability of SOX2 in GBM, thereby promoting the stemness of glioma stem cells (GSCs)." (PMID 34336690, 2021). "In glioma, lncRNA NEAT1 is upregulated, which can promotes tumor progression by inhibiting miR-132 to promote SOX2 expression." (PMID 34091587, 2021). "In tumor subgroups based on SOX2 and SFRP2 transcript levels in the TCGA and The Chinese gliomas genome atlas (CGGA) glioblastoma datasets, the respective SFRP2high/SOX2low subgroups were enriched with mesenchymal subtype tumors." (PMID 34021259, 2021). "Co-immunofluorescence (co-if) was therefore performed to further examine the extent of BTK, SOX2, and CD163 co-expression within individual cells in GBM and a low-grade glioma." (PMID 34645618, 2021). "Recently, we have shown the novel tGLI1 isoform to promote the glioma stem cell population via upregulation of CD44 and the breast cancer stem cell population through upregulation of CD44, Nanog, OCT4, and Sox2 (Section 6)." (PMID 32957513, 2020). "In the first series of experiments, GB primary cell cultures from patient specimens were characterized to confirm the presence of typical glioma markers, such as GFAP and SOX2." (PMID 31986121, 2020). "Previously, we have shown the increased levels of stem cell genes, including SOX2, OCT4, and GLI1 in these glioma cell lines that coincide with the presence of the CD44 and TNC in all the exosome samples from CCM." (PMID 32708613, 2020). "These spinal tumors expressed classical glioma markers, such as GFAP, Sox2, Olig2, and PDGFRa, and had a lower proliferative index than the corresponding brain tumors." (PMID 32727536, 2020). "Consistent with the role of Sox2 as a transcription factor required for tumorigenicity, TAT-Cx43266–283 reduced the number and stemness of human glioma cells at 30 days post-implantation." (PMID 31883012, 2020). "In glioblastoma, METTL3 facilitates the maintenance and radiation resistance of glioma stem-like cells via increasing the m6A modification of SRY-box transcription factor 2 (SOX2), which enhances the stability and protein expression of SOX2 mRNA." (PMID 33372610, 2020). "In fact, chromosome 3q26 gene products SRY-Box Transcription Factor 2 (SOX2) and OPA1 were found to be differentially regulated in invasive gliomas." (PMID 33233365, 2020). "Indeed, while the human genome comprises several thousand potential docking sites for SOX2, as predicted by an in silico search in advanced human glioma cells, an effective association with no more than 489 protein coding genes and 105 pre-miRNAs was experimentally determined by ChIP-seq." (PMID 32664542, 2020). "Gene expression of glioma samples revealed enrichment of a stemness signature that included the stemness markers NANOG, OCT4, SOX2, and BMI1 that correlated with tumor grade." (PMID 32957513, 2020). "LGG85 cells grow as neurospheres, express nestin (NES), an intermediate filament specific for neural immature cells, as well as two transcription factors highly expressed in gliomas (OLIG2, SOX2)." (PMID 32218467, 2020). "Several studies reported high levels of SOX2 expression in glioblastoma multiforme (GBM; WHO IV) than in the low-grade gliomas (LGGs)." (PMID 30517668, 2020). "To this end, we focused in glioma, because SIX1 and SOX2 are frequently overexpressed in these tumors and they are both specifically enriched in glioma stem cells." (PMID 30723235, 2019). "We and others have shown previously that sphere cultures expanded from glioma LN18 cells in serum-free medium with growth factors are characterized by the higher expression of pluripotency markers (NANOG, POU5F1, SOX2, CD133)." (PMID 30654849, 2019). "The mRNA and protein expression levels of Nestin, SOX2, and Oct4 were markedly up-regulated in these stem-like cells/spheroids (P < 0.05), indicating their close similarity to GSCs and that bortezomib might inhibit the stemness of glioma cells in a dose-dependent manner." (PMID 31796105, 2019).
glioma (continued). "Further studies with human glioma cells have confirmed these observations and clearly support the link of the pro-tumorigenic effect of SIX1 with senescence escape and SOX2-mediated self-renewal." (PMID 30723235, 2019). "AP-2α functions as a novel tumor suppressor to inhibit the stemness of glioma cancer cells by inhibiting the Nanog/Sox2/CD133 regulatory axis and decreasing the resistance of glioma cells to TMZ by blocking the IL6/Jak2/STAT3 signaling pathway." (PMID 31534499, 2019). "Inhibition of the Notch signaling pathway also impedes the maintenance of glioma stem cells and tumorsphere formation, in addition to reducing the expression of the glioma stem cell markers CD133, SOX2 and nestin." (PMID 31683669, 2019). "The treatment of glioma cells with cyclopamine, GANT61 or siRNA against GLI1, GLI2, or GLI3 significantly decreased the expression of GLI1, FOXM1, BMI1, SOX2, and OCT4, involving in the maintenance of the stem cell state." (PMID 30730955, 2019). "We have previously implemented a protocol to cultivate LN18 sphere cultures enriched in glioma CSCs which expressed higher levels of the pluripotency markers: NANOG, POU5F1, SOX2, and CD133 as compared to the parental/adherent tumor cells." (PMID 30654849, 2019). "Glioma CSCs as neural stem cells (NSCs), express stem cell markers such as CD133, SOX2, KLF4, and Nestin." (PMID 31661894, 2019). "Expression of glioma stem-markers, such as CD133, Nestin, and Sox2 is significantly increased in tumours growing in suspension, as neurospheres." (PMID 29518912, 2018). "In contrast, the expression of Ki67 and STAT3 target genes (CCND1 and SOX2) were significantly reduced in the MH2-treated xenografts, indicating a therapeutic effect of TAT-MH2-NLS protein for glioma." (PMID 29950561, 2018). "We expanded GSCs from glioma LN18 cells in serum-free medium with growth factors and confirmed the higher expression of pluripotency markers (NANOG, SOX2, CD133) in GSCs-enriched spheres, as previously shown." (PMID 30450051, 2018). "In the study of glioma (GBM), it was found that overexpression of SOX2 can significantly enhance the stem cell phenotype of GBM, while silencing the expression of SOX2 by RNAi technology can inhibit the proliferation of GBM stem cells and deactivate them." (PMID 30344611, 2018). "In previous studies BIX01294 was shown to stimulate sphere formation and increase SOX2 and CD133 expression in CD133-positive glioma stem cells." (PMID 30450051, 2018). "Mechanistically, we found an inverse correlation between PR-LncRNA expression and SOX1, SOX2 and SOX9 stem cell factors in human glioma biopsies and in glioma cells in vitro." (PMID 30143669, 2018). "Fractionated radiotherapy has been reported to increase SOX2 and Notch expression through NOS2/NO system upregulation, leading to glioma resistance to radiotherapy." (PMID 30227679, 2018). "Validation in a broader cohort of patients was supported by an in silico analysis of the REMBRANDT glioma dataset, which showed a strong positive correlation between KDM2B expression with both CD133 and SOX2." (PMID 29360266, 2018). "IMP3 silencing also resulted in the downregulation of four glioma reprogramming transcription factors- OLIG2, POU3F2, SOX2 and SALL2 in GSCs." (PMID 28465487, 2017). "Research has shown that some stemness markers such as L1CAM (CD171), Bmi-1, SOX2, and CD44 can also regulate glioma radioresistance." (PMID 29246031, 2017). "In our study, we found that reduced LINC00461 expression reduced expression levels of some EMT markers (N-cadherin and ZEB1) and several other factors related to glioma “stemness” (CD44, SOX2, Nestin)." (PMID 29137410, 2017). "We found that the delivery of CMV70-3P inhibitor significantly inhibited SOX2 expression in U118CMV infected and GBM13 glioma stem cells (p < 0.029 and 0.008) without altering the expressions of CD133, NESTIN and OLIG2." (PMID 27517625, 2017).